INS (insulin)
Diseases named in the same sentence as INS in open-access papers (continued):
Sharing a sentence is not in itself a finding about the gene and the disease.
type 2 diabetes (continued). "In type 2 diabetes, a deterioration of insulin secretion and the development of peripheral insulin resistance lead to the development of hyperglycaemia." (PMID 31275246, 2019). "STZ partly destroys the beta cells that secrete inadequate amounts of insulin, creating type 2 diabetes." (PMID 30805250, 2019). "Considering the benefits of the newer non-insulin antidiabetic agents, sulfonylureas will likely have a more limited role in the treatment of type 2 diabetes." (PMID 31412090, 2019). "Then we reviewed effects of the existing insulin therapy regimens on glycemic control and we assessed existing algorithms aimed at calculating prandial insulin doses in people with type 1 and type 2 diabetes." (PMID 30871141, 2019). "With MITI, an automated system sends a text message every week day to patients who have uncontrolled type 2 diabetes and need an adjustment of their basal insulin by asking for their FBG levels." (PMID 31368439, 2019). "In type 2 diabetes, the incretin effect is diminished and in parallel, post-prandial insulin secretion is deteriorating." (PMID 31275246, 2019). "Despite clear clinical, biochemical and genetic characteristics of type 2 diabetes, 30% of those meeting study criteria for type 2 diabetes were commenced on insulin at diagnosis." (PMID 30969375, 2019). "In 2016, a study on elderly individuals which was conducted in China ascertained that Se levels relate to type II diabetes due to increased glucose levels and their resistance to insulin." (PMID 31998571, 2019). "In a previous clinical trial, 500 mg of berberine 3 times daily was prescribed to treat 48 adults who had poorly controlled type 2 diabetes under a single or combination treatment regimen including metformin, sulfonylureas, acarbose, and insulin therapy." (PMID 31415655, 2019). "Type 2 diabetes (T2D) results from the body’s ineffective use of insulin and accounts for 85% to 95% of all diabetes, and is largely the result of excess body weight and physical inactivity." (PMID 29685153, 2018). "Type 2 diabetes is characterised by abnormal glucose metabolism brought about by resistance to insulin action and an inadequate compensatory insulin secretory response." (PMID 30086771, 2018). "In type 2 diabetic patients, resveratrol supplementation reduces markers of oxidative stress, which are accompanied by an improvement of insulin sensitivity, blood pressure, and cardiovascular function." (PMID 30400297, 2018). "Herein, the rats co-treated with HFD and DEX exhibited a loss of body weight, and an increase of fasting blood glucose, serum insulin levels, and triglycerides, which are typical features of type 2 diabetes." (PMID 30583568, 2018). "Presently, sulfonylureas and meglitinide as insulin secretagogues are being used for treatment of type 2 diabetes in patients (Winzell and Ahrén, 2007)." (PMID 29492402, 2018). "Previous works have shown that chromium picolinate (CrPic) supplementation modulated insulin, glucose and lipid metabolism in type 2 diabetic rats." (PMID 30219082, 2018). "This corresponds to our previous report on the ability of the ethyl acetate fraction of C. volubile methanolic extract to reduce blood glucose level and improve insulin secretion and β-cell function in type 2 diabetic rats." (PMID 29449808, 2018). "Both experimental and clinical studies now converge to show that several ILs contribute to the pathology and physiology of Type 2 diabetes through their interaction with insulin signaling pathways and β-cell functions." (PMID 30598026, 2018). "In DEVOTE, patients with type 2 diabetes were randomised to receive insulin degludec or insulin glargine U100 once daily." (PMID 28913575, 2018). "When islet β-cell failure occurs in patients with type 2 diabetes, insulin therapy becomes inevitable." (PMID 29520742, 2018).
type 2 diabetes (continued). "In the multi-country concept elicitation study, patients who have been treated with non-insulin injectable medication for type 2 diabetes reported a wide range of injection device features that influenced their perceptions of the injection experience." (PMID 30294713, 2018). "Patients with diabetes type 2, prescribed with lixisenatide and basal insulin were divided in three groups (premixed insulin, basal bolus insulin and basal oral therapy (BOT)." (PMID 29563974, 2018). "Impaired responsiveness to insulin leads to IR, which typically occurs at the level of IRs-1, has been observed in metabolic disorders, including type 2 diabetes and NAFLD." (PMID 30275422, 2018). "Type 2 diabetes is the commonest form of this disease which is characterized by insulin resistance or reduced insulin sensitivity leading to hyperglycemia." (PMID 30356437, 2018). "The identification of individuals with latent autoimmune diabetes of adults (LADA) is relevant for therapeutic decisions, since these individuals need insulin therapy much earlier than those with classical type 2 diabetes." (PMID 29417185, 2018). "Type 2 diabetes is characterized by insufficient insulin secretion to compensate for peripheral insulin resistance." (PMID 30190473, 2018). "Currently, all people with type 1 diabetes and many with type 2 diabetes require insulin therapy in order to achieve glycaemic control." (PMID 30116732, 2018). "Low rCP is associated with increased glucose variability and hypoglycaemia in patients with insulin-treated type 2 diabetes and represents a practical, stable and inexpensive biomarker for assessment of hypoglycaemia risk." (PMID 28983693, 2018). "Type 2 Diabetes Mellitus (T2DM) is a metabolic disease characterized by impaired insulin secretion and/or action in target organs that leads to elevations in blood glucose levels." (PMID 29449530, 2018). "In previous studies comparing IDegAsp with BIAsp30 twice daily among insulin users with type 2 diabetes, IDegAsp was superior in terms of maintaining a low fasting plasma glucose level with a low daily insulin dose." (PMID 30127860, 2018). "In this respect, compared with insulin monotherapy, the addition of metformin to insulin therapy improves metabolic control and decreases complications in type 2 diabetes." (PMID 29338714, 2018). "Clinical practice guidelines recommend maintaining a hemoglobin A1c (HbA1c) level less than 7%, but among type 2 diabetes patients using insulin, two-thirds have HbA1c above 7% and one-third have HbA1c above 9%." (PMID 32685571, 2018). "A primary treatment strategy for type 2 diabetes relies upon improving insulin sensitivity, such as with the thiazolidinedione-class drug rosiglitazone (RG), a powerful insulin sensitizer." (PMID 30627576, 2018). "In most registries, normal clinical practice during our study period would have been to switch women who became pregnant while taking metformin for type 2 diabetes to insulin." (PMID 29941493, 2018). "Short-term insulin intensive therapy plays a role in alleviating the increased inflammation reaction in type 2 diabetics." (PMID 29641741, 2018). "Schematic illustration of tropisetron's (5-HT3 antagonist) modulation of the insulin and Wnt/β-catenin signaling pathways both peripherally and centrally in type 2 diabetes." (PMID 35539384, 2018). "Family history, obesity, impaired insulin action and secretion are strong predictors of type 2 diabetes." (PMID 29274011, 2018). "Other studies have identified loci associated with MetS traits, including central obesity, insulin responsiveness, and type 2 diabetes, as well as lipid profiles in diverse populations." (PMID 29643945, 2018). "The prevalence of type 2 diabetes is on the rise; however, the availability of providers with expertise in insulin therapy is globally stable and low." (PMID 29682315, 2018). "In both critical illness and type 2 diabetes, hyperglycemia results from reduction in the first-phase insulin response." (PMID 30071851, 2018).
type 2 diabetes (continued). "Medical treatment of type 2 diabetes in pregnancy is generally restricted to insulin, as data on the safety and efficacy of oral hypoglycemic agents in pregnancy are limited." (PMID 30541506, 2018). "This study was done by asking 102 insulin-treated patients with Type 2 diabetes who had experienced hypoglycaemia in the preceding 2 months their subjective experience of the presence of 22 symptoms of hypoglycaemia during a ‘typical’ hypoglycaemic episode." (PMID 28918198, 2018). "The situation is further worsened when pancreatic beta cells initially increase insulin production and eventually fail, leading to type 2 diabetes." (PMID 29793507, 2018). "Basal insulin is a recommended insulin regimen for patients with type 2 diabetes according to the guidelines of Western countries." (PMID 30127860, 2018). "When cats develop Type 2 diabetes, they become insulin resistant and therefore have lowered insulin sensitivity." (PMID 29971046, 2018). "Consistently, many previous studies reported that type 2 diabetes and insulin resistant subjects have decreased insulin clearance." (PMID 29791512, 2018). "The present study aimed to evaluate plasma uric acid levels in type 2 diabetic patients and to determine the effects of hypoglycemic drugs and pharmacologic insulin on plasma uric acid concentration." (PMID 30349765, 2018). "In contrast, the linear associations of 2hPG, loge fasting insulin and loge HOMA-IR with incident type 2 diabetes suggest that the risk is lowered with lower levels." (PMID 29018885, 2018). "The incapacity of beta-cells to compensate for the impaired insulin action is previously identified as the key defect leading to subsequent type 2 diabetes." (PMID 29274011, 2018). "Information from observational studies on large groups of people with type 2 diabetes suggest an inexorable worsening of blood glucose control with a need for increasing numbers of tablets and, eventually, insulin." (PMID 29143063, 2018). "Safety and effectiveness of non-insulin glucose-lowering agents in the treatment of people with type 2 diabetes who observe Ramadan: a systematic review and meta-analysis." (PMID 29527102, 2018). "To this aim we generated two Drosophila models of type 2 diabetes, the first by impairing insulin signaling and the second by rearing flies in high sugar diet." (PMID 30061626, 2018). "There is strong evidence that the protein content of GLUT4 is an important contributory factor to the reduction in human adipose tissue insulin sensitivity in obesity and type 2 diabetes." (PMID 29193093, 2018). "After almost 100 years post insulin invention, it is still a cornerstone for type 2 diabetes treatment to maintain an optimal blood glucose level." (PMID 29755520, 2018). "Type 2 diabetes (T2DM) is characterized by chronic hyperglycemia caused by a combination of insulin resistance and inadequate compensatory insulin secretion." (PMID 29529994, 2018). "But nothing is known about its effect on type II diabetes, especially on insulin resistance condition." (PMID 30305829, 2018). "First generation TZDs (“insulin sensitizers”) were introduced to improve insulin sensitivity in type 2 diabetes." (PMID 29793507, 2018). "All together, these results demonstrate that bilateral CSN resection improves insulin sensitivity and glucose metabolism in a model of type 2 diabetes." (PMID 29332196, 2018). "Intramuscular fat (IMF) content and carcass composition play important roles in metabolic and physiological processes in mammals because they influence insulin sensitivity and consequently prevalence of metabolic diseases such as obesity and type 2 diabetes." (PMID 29945546, 2018). "Low levels of glucagon and vimentin co-expression, and even lower insulin-vimentin co-expression, have been recently reported in normal human pancreas while a higher co-expression was found in type 2 diabetes." (PMID 29360826, 2018).
type 2 diabetes (continued). "Additional aims are to assess the side effects and safety of insulin and metformin among pregnant women with overt type 2 diabetes and to compare gestational weight gain among women treated with metformin plus insulin versus insulin alone." (PMID 30541506, 2018). "Maturity onset diabetes of the young (see Glossary) is characterised by impaired insulin secretion with minimal impact on insulin action, and is commonly caused by dominant-negative mutations in the gene encoding hepatocyte nuclear factor 1α (HNF-1α)." (PMID 29419487, 2018). "The progression of beta cell failure to type 2 diabetes is preceded by an early positive increase in the insulin secretory response to glucose, which is only later followed by a loss in the secretion capacity of pancreatic islets." (PMID 30166558, 2018). "Patients with type 2 diabetes starting on a given dose of basal insulin are asked to check their morning fasting blood sugar at home daily while taking that particular dose." (PMID 29555621, 2018). "For type 2 diabetics, cells from liver and muscles display a decreased response to the insulin stimuli, i.e., they are insulin-resistant, and the resulting decreased glucose uptake leads to hyperglycemia." (PMID 30018269, 2018). "Type 2 diabetes mellitus (T2DM) is a complex and progressive disease due to a progressive loss of β-cell insulin secretion frequently on the basis of insulin resistance that manifests clinically as hyperglycemia." (PMID 29915538, 2018). "To further explore the role of insulin in peripheral lipolysis, we studied Gpihbp1 mRNA and protein expression in a well-established type 2 diabetic mouse model, the insulin resistant Leprdb/db and control Leprdb/m mice." (PMID 30408040, 2018). "How and when patients with type 2 diabetes treated with basal insulin received treatment intensification was also described." (PMID 30226870, 2018). "Research in the UK demonstrated significant changes in understanding and attitudes amongst people of South Asian origin who viewed a DVD about insulin in type 2 diabetes, produced as a collaboration between TME and the University of Leicester." (PMID 28649416, 2018). "Exercise has also been shown to improve glycemic control and insulin sensitivity in patients with type 2 diabetes." (PMID 29520251, 2018). "External insulin replacement through multiple daily injections (MDI) or continuous subcutaneous insulin delivery (CSII) using insulin pumps, is mandatory in type 1 diabetes and is increasingly used in type 2 diabetes." (PMID 32232090, 2018). "Type 2 diabetes is due to a partial failure of insulin not only to repress glucose production by the liver but also to promote glucose uptake by muscle." (PMID 29343628, 2018). "As expected, type 2 diabetic patients showed higher levels of fasting glucose, HbA1c, fasting insulin and HOMA-IR index than control subjects (p < 0.001)." (PMID 30115863, 2018). "Another recent study showed that 8 weeks of calorie restriction (600 kcal/day) in severely obese patients with type 2 diabetes, normalised pancreatic beta-cell function and improved insulin suppression of liver glucose production." (PMID 29784059, 2018). "Reduced insulin secretory capacity and impaired beta-cell compensation are thought as the two major pathophysiological mechanism of beta-cell dysfunction in type 2 diabetes." (PMID 30564288, 2018). "Type II diabetes is characterized by the combination of insulin unresponsiveness in the target tissue and the failure of pancreatic beta cells to secrete sufficient insulin." (PMID 30087301, 2018). "For people with type 2 diabetes poorly controlled by metformin, early addition of the long-acting insulin analogue insulin glargine leads to effective glycemic control and improved β-cell function." (PMID 30420969, 2018). "Oral antidiabetic drugs (OADs) for patients with type 2 diabetes decrease blood glucose level through increased insulin sensitivity or accelerated insulin secretions." (PMID 30261876, 2018).
type 2 diabetes (continued). "Patients with a high BMI were more likely to have Type II diabetes, take metformin, and take insulin." (PMID 29423104, 2018). "Large clinical trials have provided evidence that AT1R blockers improve insulin sensitivity and help prevent type 2 diabetes." (PMID 29971102, 2018). "Secondly, the four reviews varied greatly in terms of the type of telehealth interventions, duration of follow-up, study sample size, baseline HbA1c levels, and/or insulin- and non-insulin-dependent population with type 2 diabetes." (PMID 29940936, 2018). "Patients with type 2 diabetes mellitus (T2DM) under intensive basal-bolus insulin regimens face similar problems." (PMID 29674306, 2018). "In this cohort study of a 50–75-year-old Dutch population, FPG was most strongly associated with incident type 2 diabetes followed by 2hPG, HbA1c, HOMA-IR and fasting insulin." (PMID 29018885, 2018). "We therefore attempted to evaluate the effect of intranasal insulin on LH concentrations in men with type 2 diabetes." (PMID 30515210, 2018). "Overall, based on self-reported type and current insulin use, 0.55% of U.S. adults had diagnosed type 1 diabetes, representing 1.3 million adults; 8.6% had diagnosed type 2 diabetes, representing 21.0 million adults." (PMID 29596402, 2018). "An RCT of CSII vs MDI in type 2 diabetes (OPT2MISE) did show CSII to be of benefit in those who were unable to improve control despite high doses of insulin, although the incidence of hypoglycaemia was low in both groups." (PMID 29423581, 2018). "In patients with type 2 diabetes, different time-action profiles and distinct patterns regarding the suppression of endogenous insulin secretion and lipolysis have been reported." (PMID 30114246, 2018). "Insulin and IGF resistance due to type 2 diabetes in human patients significantly increases the risk of developing dementia, and is associated with regional brain atrophy." (PMID 30061810, 2018). "Not surprisingly, in clinical studies that supervise treat-to-target insulin therapy in patients with type 2 diabetes, individual daily requirements average at 1.5–2 units per kilogram with a wide variance of distribution." (PMID 29682315, 2018). "Dipeptidyl peptidase-4 (DPP-4) inhibitors, such as alogliptin, which increases incretin levels to inhibit glucagon release leading to increased insulin secretion are also a common treatment for type 2 diabetes." (PMID 30534081, 2018). "Currently, the Canadian multi-centre MiTy trial is assessing the possible benefit of adding metformin to insulin for type 2 diabetes in the first or second trimesters." (PMID 29973490, 2018). "Type 2 diabetes represents a significant public health issue, with increasing prevalence in developing countries while adherence to insulin treatment remains a challenge." (PMID 29520741, 2018). "Type 2 diabetes is a metabolic disease characterized by hyperglycemia resulting from either or both impaired β-cell insulin secretion and increased peripheral insulin resistance; particularly in muscle, liver, and fat." (PMID 29867762, 2018). "Impairment of the first phase of insulin secretion has long been recognized as an early indication of β-cell dysfunction during type-2 diabetes." (PMID 29459424, 2018). "In conclusion, we have shown that the ratio of valine to PC ae C32:2 in blood is positively associated with insulin secretion, HOMA-IR and prevalent type 2 diabetes." (PMID 28936587, 2018). "One of the pathological features of cardiac muscle in type 2 diabetes is attenuated insulin-stimulated glucose uptake." (PMID 30138395, 2018). "People with type 2 diabetes (T2D) often require oral antihyperglycemic agents and/or insulin to achieve and maintain optimal glycemic control." (PMID 30112462, 2018). "Recent studies have also suggested that green tea increases insulin sensitivity and glucose metabolism, helping to prevent type 2 diabetes from developing." (PMID 30591664, 2018).